CXCL8 (C-X-C motif chemokine ligand 8)
Diseases named in the same sentence as CXCL8 in open-access papers (continued):
Sharing a sentence is not in itself a finding about the gene and the disease.
tumor (continued). "Analysis of CXCL8 expression through immunohistochemistry showed that CXCL8 was primarily found in tumor cells, showing a trend of increased but not statistically significant CXCL8 expression in Fusobacterium-high tumors." (PMID 40895532, 2025). "When M1 MEVs are introduced into the tumor microenvironment, they influence the surrounding M2 macrophages to adopt a more pro-inflammatory, tumor-fighting state by increasing the secretion of cytokines such as TNF-α and upregulating pro-inflammatory markers like CXCL8." (PMID 40330466, 2025). "CSCs activate the expression of the chemokines CXCL1, CXCL2, and CXCL8 through the ERK pathway, facilitating the recruitment of MDSCs within the tumor, whereas MDSCs help maintain the stem cell characteristics of cancer cells, promote angiogenesis, and assist in CSC metastasis and colonization." (PMID 41368628, 2025). "Functionally, SPP1+ TAMs play a central role in promoting tumor cell epithelial-mesenchymal transition (EMT), angiogenesis, intravasation, metastasis, and immunosuppression through the secretion of factors including SPP1, CCL18, CXCL8, TNF-α, and IL-1β." (PMID 41459510, 2025). "Furthermore, IL-8 (CXCL8) can further upregulate MMP1 expression by activating the STAT3 signaling pathway, thereby enhancing tumor cell invasiveness." (PMID 40809844, 2025). "Additionally, NK cells secrete chemokines such as CCL1, CCL2, CCL3, CCL4, CCL5, and CXCL8, which contribute to the recruitment of T cells and macrophages into the TME, and tumor cell destruction." (PMID 40141437, 2025). "Interestingly, the scRNA‐seq data revealed the upregulation of CXCL2, CXCL3, CXCL8, and CCL4 in metastatic tumor cells compared to primary tumor cells or normal cells." (PMID 39985269, 2025). "NF-κB activation triggers inflammatory pathways, establishing a positive feedback loop with a rise in chemokine expression (e.g., CXCL8 and CCL2), nitric oxide synthase (NOS), COX-2, and inflammatory mediators (IL-6, IL-8, and TNF-α), thereby fostering tumor development." (PMID 40420174, 2025). "In addition, G31P-mediated CXCR1/2 inhibition disrupts the pathological feedback loop in the tumor microenvironment, where ELR+ CXC chemokines (CXCL1/8) activate CXCL8, leading to EGFR transactivation and sustained inflammatory signaling." (PMID 41425704, 2025). "The impact of these drug-induced increases in CXCL8 on MM tumorigenesis has not been thoroughly studied, but it is clear that CXCL8 has both pro- and anti-tumor properties in MM." (PMID 40940985, 2025). "Notably, depletion of GPATCH3 led to significant upregulation of CXCL8, CCL5, LAG3, and PVRL2 —genes with well-established roles in immune cell recruitment, immune checkpoint signaling, and tumor–immune interactions." (PMID 40861452, 2025). "Recent research indicates that the CXCL8/CXCR2 signaling pathway is crucial for the recruitment of myeloid-derived suppressor cells (MDSCs) into the tumor microenvironment (TME), with MDSC accumulation contributing to immune suppression and tumor progression." (PMID 40006729, 2025). "Tissue-specific subsets included CXCL8 + breast fibroblasts [most abundant subset (>85%) in normal breast tissue], NPNT+ (alveolar) lung fibroblasts and F3+/ADAMDEC1 + colonic/gastric fibroblasts (all found in normal and tumour samples)." (PMID 39757146, 2025). "CXCL8 recognizes and activates the G protein-coupled receptors (GPCRs) CXCR1/2, thereby inducing the activation and trafficking of inflammatory mediators and facilitating tumour progression, invasion, and metastasis." (PMID 39962077, 2025). "Metastatic tumor cells also exhibit high expression of heterogeneous nuclear ribonucleoprotein AB (hnRNPAB), which stabilizes MYC mRNA and promotes neutrophil recruitment at extravasation sites through the secretion of CXCL8." (PMID 40027151, 2025).
tumor (continued). "Neutrophils, particularly those polarized toward the N2 phenotype, are key contributors to tumor angiogenesis through the secretion of multiple pro-angiogenic factors, including FGF2, VEGF-A, ANGPT1, CXCL8, HGF, and MMP9, which collectively facilitate tumor vascularization and metastatic spread." (PMID 40564191, 2025). "In ENKTCL, MDSCs are recruited and activated within the tumor microenvironment (TME) by EBV- and tumor-driven factors, including GM-CSF, IL-6, TGF-β, CCL2, and CXCL8, which promote both monocytic (M-MDSC) and granulocytic (PMN-MDSC) subtypes and enhance their suppressive phenotype." (PMID 41303704, 2025). "In addition, the levels of CXCL1, CXCL8, VEGFA, and VEGFB related to monocyte recruitment and angiogenesis were higher in patients with advanced stages than in those with tumor stage 1." (PMID 40860188, 2025). "EFNA1 may drive tumor progression via the MAPK signaling pathway, CXCL8 could influence immune evasion through NOD-like receptor signaling, and PPP1R14A may contribute to tumor invasion by modulating extracellular matrix remodeling." (PMID 40406253, 2025). "Others have shown in tumor cell lines and animal models that CRC tumor cells express one of the receptors for CXCL8, C-X-C motif chemokine receptor 2 (CXCR2), and that stimulation with CXCL8 induces tumor cell growth and metastasis." (PMID 40895532, 2025). "Furthermore, studies have shown that combined treatment with CXCL8/CXCR2 inhibitors, such as SX-682, and ICIs can significantly enhance anti-tumor efficacy by reducing MDSC recruitment." (PMID 40006729, 2025). "The PERK-dependent activation of C/EBPδ creates prolonged activation of CXCL8 (also known as IL-8) and CCL20, two well-known tumor-promoting chemokines that have been shown to recruit regulatory T cells and polarize macrophages into immunosuppressive M2 phenotypes." (PMID 41301006, 2025). "Notably, members of the CXC chemokine family, including CXCL1, CXCL2, CXCL3, CXCL5 and CXCL8, function through the activation of CXCR1 and CXCR2, playing a key role in promoting tumour angiogenesis." (PMID 39161078, 2025). "The presented results indicate the significant correlation between the CXCL12, CXCR4, CXCL8/CXCR2, M-CSF, MMP-2, MMP-9 ADAM17, ADAMTS-6, and CLDN7 levels and tumor stage, as well as the clinicopathological parameters of OC, such as the presence of lymph node and/or distant metastases." (PMID 38673838, 2024). "Therefore, we used the tumor IMmune Estimation Resource (TIMER) Web Server to investigate FN1, CXCL8, IL1β, and ITIH4's function in the Comprehensive Analysis of tumor-infiltrating Immune Cells." (PMID 38637796, 2024). "In addition to the well-known angiogenic effects of activated CXCL8, it also enhances the expression of ICAM1 in the context, which aids tumour cell adhesion to endothelial cells and liver metastasis." (PMID 39025845, 2024). "Besides tumor cells attracting TAMs by releasing chemokines and cytokines, the TAMs themselves produce chemotactic mediators, such as CCL5, CXCL8, IL-1 receptor antagonist, CCL18, CXCL2 and CXCL3, which also contribute to monocyte/macrophage recruitment." (PMID 39513610, 2024). "Furthermore, CXCL8 collaborates with molecules such as VEGF in the TME to collectively enhance angiogenesis, affecting tumor growth and metastasis." (PMID 38791448, 2024). "Our laboratory and others have previously demonstrated a role for the chemokine interleukin-8 (IL-8, CXCL8) in mechanisms of tumor progression in several tumor types, including as a driver of resistance to chemotherapy, EGFR-targeted therapy, and immunotherapy." (PMID 39639338, 2024). "Neutralizing CXCL8 in CM derived from MLKL-overexpressing tumour cells that were cultured alone failed to induce MET formation, as seen in WB analysis and SYTOX staining." (PMID 39025845, 2024).
tumor (continued). "In turn, TAM recruit or activate endothelial cells to produce vascular endothelial growth factor A (VEGF-A), epidermal growth factor (EGF), C-X-C motif chemokine ligand 8 (CXCL8), and CXCL12 to promote tumor angiogenesis and continuously provide nutritional support for malignant cells." (PMID 37968342, 2024). "The expression of hypoxia-related chemokines, such as CXCL12 and CXCL8, along with pro-angiogenic factors such as vascular endothelial growth factor (VEGF), produced and expressed simultaneously by tumor cells and the breast stroma, promotes the formation of abnormal vessels in tumors." (PMID 39769501, 2024). "Hence, we correlated the expression level of the tumor-upregulated gene signature, comprising HAS2, MMP9, CXCL8, CXCL11, IL1B, and IL6, with the ratio of infiltrating M1 macrophages." (PMID 38329386, 2024). "We found that CXCL8 increased ICAM1 expression in MLKL-overexpressing tumour cells that were co-cultured with macrophages, while no changes were observed when MLKL-overexpressing tumour cells were cultured alone." (PMID 39025845, 2024). "Previous evidence showed that tumor infiltrating lymphocytes, such as NK cells, intratumoral T-cell, and CD11c + cells, were related with improved survival performance, and CD206 + and CXCL8 + macrophages correlated with poor survival outcomes." (PMID 38914980, 2024). "CXCL8 modulates the TNBC immune microenvironment by controlling the infiltration of CD4+ and CD8+ T cells and increasing CD274 (PD-L1) expression, unveiling potential therapeutic targets for anti-tumor immunotherapy." (PMID 38791448, 2024). "Activated dendritic cells stimulate the formation of M2 macrophages to secret some cytokines, such as IL-6, CXCL8, VEGF, and TGF-β, which could suppress the adaptive immune response and promote tumor growth." (PMID 39060620, 2024). "These discrepancies could arise due to different sources and downstream effects of CXCL8 in HCC tumor and non-tumor tissues." (PMID 38694506, 2024). "This shift from CCL5/CXCL9/CXCL10 to CXCL8/CXCL12/CCL22 production was attributed to NFκB-mediated induction of COX2/PGE2/EP4, along with upregulation of IDO1 and IL-10, further contributing to the immunosuppressive tumor microenvironment." (PMID 39409924, 2024). "Moreover, it has been reported that the tumor-infiltrating γδT17 subset mediating pro-angiogenic IL-17 thereby inducing the expression of VEGF-A, CXCL8, GM-CSF, and TNFα release, can actively participate in the angiogenic process and the recruitment of MDSCs." (PMID 38726320, 2024). "CXCL8 up-regulation has been seen in GBM, and it has been shown that Bcl-xl-induced CXCL8 up-regulation in GBM cells is mediated through the NF-κB-dependent mechanism, consistent with other tumor research." (PMID 37692522, 2024). "Another study focused on HNSCC revealed that SPP1 + TAMs might enhance tumor intravasation and metastasis via the secretion of SPP1, CCL18, and CXCL8." (PMID 39726047, 2024). "This persistent inflammatory state in the TME contributes to tumor-supportive processes, including angiogenesis, invasion, and metastasis, which are often mediated by cytokines such as IL-6, TNF-α, and chemokines like CXCL8." (PMID 39769051, 2024). "CXCL1 and CXCL8, members of the angiogenic CXC chemokine family are highly expressed only on the border of annotated tumor regions in our study, suggesting that an immune exclusion and blockage by the tumor." (PMID 38729966, 2024). "CXCL8/interleukin 8 (IL8), a member of the CXC chemokine family, could promote tumor invasion, migration, angiogenesis, and metastasis by binding to its receptors CXCR1 and CXCR2." (PMID 39706835, 2024).
tumor (continued). "The increased Treg infiltration of the tumor was independent of TGFβ signaling, suggesting a systemic distribution of CXCL8 and IL6 produced by cancer cells, which results in increased neutrophil production, Foxp3 upregulation on T lymphocytes, and tumor trafficking through CXCR1." (PMID 39409924, 2024). "On the other hand, CXCL8 is a target for solid tumor immunotherapy, and CXCL9/10 has been demonstrated to enhance the accumulation of effector T cells at the tumor site and suppress tumor growth." (PMID 36969851, 2023). "Chemokines secreted by TAMs, including CCL3, CCL5, CCL15, CCL18, CXCL8 and CXCL12, promote tumor metastasis, angiogenesis, cancer cell survival, immunosuppression and resistance of cancer cells after chemotherapy via CCR1/5, CCR5, CCR1, CCR8, CXCR1/CXCR2, CXCR4, respectively." (PMID 36173487, 2023). "If we could examine the downstream effect of CXCR1 compared to CXCR2 when bound to CXCL8 or CXCL6, we could evaluate which downstream pathways elicit pro-CSC-like characteristics in the tumor cells." (PMID 36831112, 2023). "We also observed that MDSC-secreted VEGFA and multiple chemokines CCL2, CXCL1, CXCL2, CXCL3, and CXCL8 could act on endothelial cells via VEGFA-KDR/FLT1 and CCL2/CXCLs-ACKR1 interactions, which were crucial for tumor angiogenesis." (PMID 37475874, 2023). "However, tumor cells release other cytokines (e.g., VEGF, β-defensin, CXCL12, HGF, and CXCL8) that recruit immature DCs from the peripheral blood in the TME and, at the same time, hamper DCs’ maturation and function." (PMID 36834641, 2023). "These infiltrated immune cells and solid tumor cells release tumor-progressing cytokines (IL-6, TNF-α, TGF-β), chemokines (CCL2, CCL5, CCL18, CXCL8, CXCL12), and growth factors (EGF, PGF, IGF-1, IGF-2, PDGF) that promote tumor microenvironment immunosuppressive." (PMID 37371075, 2023). "CXCL8 interacts with CXCL1 and CXCL2 to promote the secretion of multiple proinflammatory, angiogenic, and immunomodulatory factors (including MMP and VEGF) by neutrophils, thereby promoting tumor metastasis in patients with NSCLC." (PMID 36726839, 2023). "CXCL8 mediates EMT in ovarian and gastric tumor cells by binding to its receptor so that the down-regulation of E-cadherin and up-regulation of N-cadherin reduce the adhesion between tumor cells and induce tumor cell shedding." (PMID 37377954, 2023). "Tumor cells‐secreted CXCL1 and CXCL8 recruit neutrophils and promote activation of ERK and JNK signaling pathways and expression of VEGFA and MMP9 in neutrophils, which induce tumor lymphangiogenesis and facilitate LN metastasis of tumor cells." (PMID 36670069, 2023). "For cases with upregulated CXCL8, coding for IL8 (a pro-angiogenic factor), combination treatment with an IL8 inhibitor may improve tumor growth control." (PMID 36765551, 2023). "In addition through the release of chemokines such as CXCL1, CCL5, CXCL5, CXCL8, and CXCL7 by MSCs, tumor cell migration to metastatic sites is accelerated." (PMID 36829187, 2023). "We found that NUP107 was positively correlated with chemokines such as CCL28 and CXCL8 (r = 0.310, p < 0.001), and the chemokine receptors CCR8 and CXCR4 suggesting that NUP107 overexpression may recruit immune cells to the tumor tissues." (PMID 36952458, 2023). "Moreover, tumor‐derived CXCL1 and CXCL8 increased CXCR2, ERK and JNK pathways‐dependent production of VEGFA and MMP9 in neutrophils, which led to lymphangiogenesis." (PMID 36670069, 2023). "A PKCβ involvement in the increase in CD69 levels was involved in tissue residency was also suggested, along with the production of CXCL8 chemokine, the latter reported as pro-tumorigenic in the TME by supporting tumor persistence, EMT, angiogenesis and impairment of anti-tumor responses." (PMID 37626933, 2023). "Further potential avenues proposed to block protumor effects of TANs could be achieved by targeting the CXCL-8/CXCR-1/CXCR-2 axis, or targeting substances produced by TANS which promote tumor growth." (PMID 37143649, 2023).
tumor (continued). "Following their mobilization from the bone marrow and entry into the bloodstream, MDSC are recruited into tumor tissues in part by following chemokine gradients such as CCL2 and CXCL8, and other cytokines secreted by tumor cells and immune cells within the TME." (PMID 37114134, 2023). "These included and were not limited to the chemokine genes CXCL2, CXCL3 and IL8/CXCL8, as well as the IL6 and its receptor, IL6R, which could promote inflammatory responses and also promote tumor growth." (PMID 36678826, 2023). "TNF-α is one of the most abundant pro-inflammatory cytokines followed by CXCL-8 in the oral MSC secretome, which could potentially mediate tumor development." (PMID 38170015, 2023). "Therefore, referring to macrophage categorization, mast cells are divided into anti-tumor MC1 and pro-tumor MC2 based on TNF, granzyme B (GZMB), IL9, VEGF-A, and C-X-C motif chemokine ligand 8 (CXCL8) expression." (PMID 36726981, 2022). "Neutrophil-attracting chemokines, such as CXCL1, CXCL2, or CXCL8, are induced in hypoxic tumor tissue, through the activation of hypoxia-inducible factor 1 (HIF-1α or β), and support neutrophil migration to the tumor site via CXCR1 and CXCR2 receptors." (PMID 35158807, 2022). "However, chemokines released by HCC (CXCL-2, CXCL8 and CCL25), in turn, increase the proportion of neutrophils in the TME, forming an immunosuppressive microenvironment and leading to tumour progression." (PMID 36291944, 2022). "It was also shown that CXCL8/IL8 and IL6 induced the resistance of tumor cells to chemotherapy." (PMID 36354566, 2022). "miR-20a from stromal cells directly represses the 3′UTR of CXCL8, an inflammatory chemokine secreted from interstitial fibroblasts, and its dysregulation was postulated to modulate tumor genesis, but not influence tumor outcome." (PMID 35955886, 2022). "In addition, high levels of CXCL8/IL8, IL6, and MCP-1/CCL2 secretion promoted the migration of tumor cells and macrophage-like cells, exacerbating tumor progression." (PMID 36354566, 2022). "It is well known that tumor cells secrete a variety of chemokines, such as CCL2, CXCL1, CXCL8, etc." (PMID 36591450, 2022). "In addition to promoting angiogenesis, the CXCL8/CXCR2 axis also exerts multiple effects on proliferation, invasion, and migration of tumor cells." (PMID 35898871, 2022). "studies indicated that NK cells can also produce chemokines, C-C-motif ligands such as CCL3, CCL4, CCL5, X-C-motif chemokine ligand 1 (XCL1) and C-X-C-motif chemokine ligand 8 (CXCL8), which attract a variety of immune cells to transformed tissues and inhibit tumor progression." (PMID 36741415, 2022). "It has been shown that IL-8 (also known as CXCL-8) promotes the formation of the TME, which could facilitate the generation of tumor cells and the invasiveness of cancer by enhancing the level of arginase in myeloid-derived suppressor cells." (PMID 36286020, 2022). "Studies have shown that CCL7, CXCL8 and CXCL12 also recruit m-MDSCs to tumor sites." (PMID 35493517, 2022). "CXCL8 secreted by primary ESCC cells can inhibit the function of natural killer cells (NK cells) through the STAT3 pathway, leading to tumor immune escape; therefore, immune-boosting therapeutic strategies targeting CXCL8 may benefit ESCC patients." (PMID 36295640, 2022). "Therefore, CXCL8 has already been described as a pro-tumorigenic chemokine by impacting cancer cells and modifying TME to promote tumor progression and metastasis." (PMID 35372515, 2022).